RGS10 (regulator of G protein signaling 10)
Diseases named in the same sentence as RGS10 in open-access papers (continued):
Sharing a sentence is not in itself a finding about the gene and the disease.
tumor (9 papers, 2009 to 2024). "Here, we initially observed elevated levels of pro-inflammatory cytokines (most notably TNF), infiltration of inflammatory cells, and upregulation of four GPCR-associated genes (CCR10, P2RY8, ARRB1, and RGS10) in human HCC tumor and paracancerous specimens." (PMID 29445190, 2018). "Immunohistochemistry showed LCN2, snail, and vimentin protein expression were increased and E-cadherin protein expression was decreased in tumor tissues derived from RGS10-depleted SKBR3 cells compared to NC." (PMID 39145770, 2024). "Inhibition of DNMT1 restores expression of tumor suppression-related genes such as p16 and RGS10 and contributes to reduced cancer cell viability, decreased invasive capability, and enhanced treatment sensitivity." (PMID 27087738, 2016). "The suppression of RGS10 is due to DNA hypermethylation and histone deacetylation, two important mechanisms that contribute to silencing of tumor suppressor genes during cancer progression." (PMID 24475290, 2014). "Thus, RGS10 functions as a tumor suppressor by blunting endogenous survival pathways, with the level of expression of endogenous RGS10 playing a critical role in the determination of apoptosis or survival." (PMID 24475290, 2014). "The growth of tumors derived from RGS10-depleted SKBR3 cells was significantly increased compared to NC, manifested by larger tumor size compared to NC." (PMID 39145770, 2024). "We further demonstrate that RGS10 and RGS17 expression regulates the cellular toxicity of multiple cytotoxic chemotherapeutics, which ultimately enhances the viability of these tumor cells in the presence of chemotherapy." (PMID 21044322, 2010). "Thus, we hypothesize that RGS10 and RGS17 function as tumor suppressors by blunting endogenous survival pathways." (PMID 21044322, 2010).
cancer (7 papers, 2010 to 2024). A tumor composed of atypical neoplastic, often pleomorphic cells that invade other tissues. "Markers for loss of RGS10 expression may identify cancer cells with unique response to therapeutics." (PMID 23533674, 2013). "Next, we determined RGS10 mRNA levels in cell lines representing 21 human cancers from the Cancer Cell Line Encyclopedia database." (PMID 39145770, 2024). "In the current study we analyzed expression of RGS10 isoforms in normal and cancer-derived ovarian cells and determined the changes in epigenetic marks on RGS10 promoter DNA and histones in cells with different RGS10 expression levels." (PMID 23533674, 2013). "Additional work is needed to determine if the epigenetic marks described here contribute to regulation of RGS10 expression in other cancers." (PMID 23533674, 2013). "We have recently shown that suppression of RGS10 is due in part to DNA hypermethylation and to histone deacetylation, two important gene-silencing mechanisms which contribute to the progression of many cancers." (PMID 24475290, 2014). "This suggests that RGS10 expression may suppress cancer cell growth and survival in a variety of tumors." (PMID 23533674, 2013). "We found that 30 of these genes which included Nckap1l, Ncf1, Pla2g15, Unc93b1, Lrrc33, Rgs10, Gmfg, Rbm25, C3ar1, Ccdc88b, Fam105a, Gng11, Phc1, Rasa4, Dag1, Tyrobp, Tmsb4x, Cfp, Prkd1, Gp49a, Trem2, C1qc, Lyz2, Igfbp7, Rab30, Cxcl16, Egfl7, Ube2r2, Pltp, and Cfb, showed a relation with cancer." (PMID 32812032, 2020). "Not surprisingly, knock-down of RGS10 alone did not rescue cell viability, consistent with the broad range of HDAC and DNMT target genes in cancer cells." (PMID 24475290, 2014).
infection (3 papers, 2021 to 2025). The state of being infected such as from the introduction of a foreign agent such as serum, vaccine, antigenic substance or organism. "Rgs10-/- mice showed increased susceptibility to lethal infection with the PR8 H1N1 virus exhibiting increased weight loss and mortality associated with delayed viral clearance as well as exacerbated lung inflammation and tissue damage." (PMID 34912341, 2021). "At day 5 post-PR8 infection, Rgs10-/- mice generated higher numbers of CD11b+ leukocytes relative to WT mice, reflecting the massive influx of the neutrophils and monocytes including inflammatory monocytes." (PMID 34912341, 2021). "Both WT and Rgs10-/- mice started losing body weight gradually from day 3 post-infection, but Rgs10-/- mice lost significantly more body weight compared to WT mice (3 through 6-day post-infection, dpi)." (PMID 34912341, 2021). "Approximately 42.3% of Rgs10-/- mice died at 5 dpi (survival rate, 57.7%) in response to 100 PFU PR8 infection compared to 11.5% of mortality rate in infected WT mice." (PMID 34912341, 2021). "While previous studies have investigated the impact of RGS10 on the pathophysiology of diverse disease models using Rgs10-/- mice, no work has studied the in vivo role of RGS10 in fighting infections." (PMID 34912341, 2021).
neurodegenerative disease (3 papers, 2013 to 2025). A disorder of the central nervous system characterized by gradual and progressive loss of neural tissue and neurologic function. "This points to deficits in RGS10 being driven, in part, by aging, which is the largest risk factor for developing neurodegenerative diseases." (PMID 39994765, 2025). "Further studies are needed to fully comprehend the regulatory capacity of RGS10 and its potential impact on diseases associated with chronic neuroinflammation, i.e., neurodegenerative diseases." (PMID 38812790, 2024). "The level of RGS10 is significantly enriched in microglia and downregulated with aging and neurodegenerative diseases." (PMID 38812790, 2024).
infectious disease (1 paper, 2021). A disorder directly resulting from the presence and activity of a microbial, viral, or parasitic agent in humans. "Our study is the first to investigate the in vivo physiological role of RGS10 in a mouse model of respiratory IAV infection and in general, any infectious disease." (PMID 34912341, 2021). "Even though RGS10 has been extensively studied in multiple animal and cellular models of these diseases, the biological function of RGS10 has not yet been explored in any infectious disease including respiratory viral infections." (PMID 34912341, 2021).
RGS10 also shares sentences with these, for which no sentence is quoted: colon cancer (2 papers); psychiatric disorder (2); alcohol dependence (1); anorexia nervosa (1); autoimmune thyroid disease (1); bacterial infections (1); bronchiolitis (1); cardiac hypertrophy (1); depression (1); Glucose intolerance (1); Hypertension (1); Impaired glucose tolerance (1); intestinal infection (1); laryngeal carcinoma (1); liver cancer (1); metabolic syndrome (1); multiple sclerosis (1); Obesity (1); rheumatoid arthritis (1); tuberculosis (1); viral infection (1).